WBP1L (WW domain binding protein 1 like)
Synonyms: C10orf26; OPA1L; FLJ20154; OPAL1; CYP17A1OS; bA753C18.3; CYP17A1-AS1
Tractability: Antibody: UniProt predicts a signal peptide or a membrane-spanning region. PROTAC: ubiquitination databases record sites on it.
Gene: Protein-coding gene on chromosome 10 (102,743,948 to 102,834,516, forward strand). Ensembl gene ENSG00000166272.
Subcellular location: Membrane
Subcellular location (Human Protein Atlas): Microtubules; Nucleoplasm
Gene Ontology:
Molecular function: protein binding; ubiquitin protein ligase binding
Biological process: CXCL12-activated CXCR4 signaling pathway
Cellular component: membrane
Genetic constraint (gnomAD): Loss-of-function variants: 17 observed, 32.6 expected, observed/expected ratio (o/e) 0.52, 90% interval 0.36 to 0.78. The upper end of that interval is the gene's LOEUF score, 0.78, which puts it in group 3 of 6, group 1 being the genes least tolerant of losing a copy. Missense variants: 389 observed, 471.11 expected, observed/expected ratio (o/e) 0.83, 90% interval 0.76 to 0.9. Synonymous variants: 173 observed, 188.96 expected, observed/expected ratio (o/e) 0.92, 90% interval 0.81 to 1.04.
Homologues: Orthologues: macaque SFXN2 (94% identical), pig WBP1L (94% identical), chimpanzee WBP1L (93% identical), rabbit WBP1L (93% identical), rat Wbp1l (90% identical), guinea pig WBP1L (89% identical), mouse Wbp1l (88% identical), dog WBP1L (87% identical), tropical clawed frog wbp1l (54% identical), zebrafish wbp1la (49% identical), zebrafish wbp1lb (44% identical). Paralogues in human: WBP1 (27% identical), PRR7 (13% identical).
Diseases named in the same sentence as WBP1L in open-access papers:
WBP1L is named in the same sentence as 16 diseases in open-access papers, as found by Europe PMC text mining. Sharing a sentence is not in itself a finding about the gene and the disease. The quoted sentences say what the papers report.
schizophrenia (11 papers, 2012 to 2021). A major psychotic disorder characterized by abnormalities in the perception or expression of reality. "We observed that only the cQTL located in the AS3MT gene colocalized with eQTLs (eQTLs of both AS3MT and WBP1L), indicating that a single genetic variant can affect the expression level of multiple genes at schizophrenia GWAS loci." (PMID 30087329, 2018). "Five previously identified loci showed significant associations with schizophrenia (MHC, WBP1L (C10orf26), DPYD-MIR137, SDCCAG8, and MMP16)." (PMID 34502224, 2021). "In the results of schizophrenia, known schizophrenia genes like WBP1L (p = 2.24E-14), TMTC1 (p = 3.75E-14), ZNF804A (p = 8.50E-14), TAOK2 (4.82E-12) and so on showed significant association." (PMID 35004692, 2021). "Additionally, we have identified eight chromatin peaks with a high probability of shared causal cQTL variant with schizophrenia GWAS variants, one of these peaks also shares genetic effects with an eQTL affecting the expression of AS3MT and WBP1L in DLPFC." (PMID 30087329, 2018).
leukemia (4 papers, 2020 to 2024). A malignant (clonal) hematologic disorder, involving hematopoietic stem cells and characterized by the presence of primitive or atypical myeloid or lymphoid cells in the bone marrow and the blood. "Another important question is the role that WBP1L potentially plays in leukaemia." (PMID 31845480, 2020). "WW domain binding protein 1-like (WBP1L), also known as outcome predictor of acute leukemia 1 (OPAL1), is a transmembrane adaptor protein, expression of which was shown to correlate with ETV6-RUNX1 translocation and favorable prognosis in childhood leukemia." (PMID 39555063, 2024). "Moreover, this subset also shares leukemia and pro‐B gene expression signatures as well as high levels of the ETV6 target genes (BIRC7, WBP1L, CLIC5, ANGPTL2) with the ER subtype, indicating that these B‐other cases are the recently identified ER‐like subtype." (PMID 33987955, 2021). "Our data do not specifically address the role of WBP1L in leukaemia." (PMID 31845480, 2020).
acute lymphoblastic leukemia (3 papers, 2020 to 2024). Leukemia with an acute onset, characterized by the presence of lymphoblasts in the bone marrow and the peripheral blood. "Initially, WBP1L expression was shown to correlate with favorable outcome in childhood acute lymphoblastic leukemia." (PMID 39555063, 2024). "This could potentially be explained by the association of increased levels of WBP1L mRNA and protein with ETV6-RUNX1 (TEL-AML1) gene fusion in B cell precursor acute lymphoblastic leukemia, which by itself is associated with favorable prognosis." (PMID 39555063, 2024).
acute leukemia (1 paper, 2024). A clonal (malignant) hematopoietic disorder with an acute onset, affecting the bone marrow and the peripheral blood. "Recently, we have characterized a novel regulator of signaling in the HSPCs, the transmembrane adaptor protein WBP1L (WW Domain Binding Protein 1 Like), also known as OPAL1 (Outcome Predictor of Acute Leukemia 1)." (PMID 39555063, 2024).
cognitive decline (1 paper, 2025). "Higher levels of NNT, MYO15A, and GCA were protective in females; greater expression of PEPD, CTNNBL1, MVB12A, XKR8, WBP1L, and GALNT7-DT were associated with faster cognitive decline in females." (PMID 40166028, 2025).
multiple sclerosis (1 paper, 2025). A progressive autoimmune disorder affecting the central nervous system resulting in demyelination. "WBP1L was previously reported in a multiple sclerosis study, whose findings indicated its participation in the pathogenesis of neurodegenerative diseases such as multiple scelerosis." (PMID 41327336, 2025).
ovarian carcinoma (1 paper, 2023). A malignant neoplasm originating from the surface ovarian epithelium. "Interestingly, none of the four top genes WBP1L, ASAP3, CNNM2, and NCAPH2 was correlated with ovarian cancer pathogenesis previously." (PMID 36856946, 2023).
cancer (1 paper, 2022). A tumor composed of atypical neoplastic, often pleomorphic cells that invade other tissues. "The more novel findings in this study were in genes (ARID5B, BAZ2B, RABGAP1, SFRP2, and WBP1L) that are associated with cancer risk and cellular differentiation." (PMID 36685876, 2022). "Five of these genes (ARID5B, BAZ2B, RABGAP1, SFRP2, WBP1L) are associated with cancer risk and cellular differentiation and have not been previously identified in MS studies." (PMID 36685876, 2022).
neoplastic diseases (1 paper, 2022). "ARID5B, BAZ2B, RABGAP1, SFRP2, and WBP1L have not been previously associated with MS risk, and all are associated with neoplastic diseases and cellular proliferation." (PMID 36685876, 2022).
WBP1L also shares sentences with these, for which no sentence is quoted: endometrial cancer (1 paper); Hypertension (1); Immunodeficiency (1); neurodegenerative disease (1); prostate carcinoma (1); T-cell leukemia (1); WHIM syndrome (1).